UCA1 (urothelial cancer associated 1)
Diseases named in the same sentence as UCA1 in open-access papers (continued):
Sharing a sentence is not in itself a finding about the gene and the disease.
tumor (continued). "In CRC, UCA1 has been implicated into not only in malignant phenotype but in chemo-resistance by interacting with cancer-promoting signaling pathways, through sponging tumor suppressor miRNAs." (PMID 34809621, 2021). "Recently research demonstrated that long non-coding RNA Urothelial cancer associated 1 (UCA1) could promote tumor cisplatin resistance." (PMID 32328192, 2020). "More importantly, UCA1 was associated with the tumor stage with a P value of 0.04." (PMID 31467637, 2019). "Interestingly, UCA1 encodes an oncogenic lncRNA that inhibits the tumour suppressive miR-143 by direct binding, and also disrupts the translation of tumour suppressor protein p27 through competitive inhibition." (PMID 31061680, 2019). "The correlation regression analysis revealed that high expression of UCA1 was associated with large tumor size (p = 0.032) and lymph node metastasis (p = 0.033), which implied that UCA1 may be involved in the growth and invasion of HCC." (PMID 31040354, 2019). "Hence, lncRNA UCA1 in body fluid samples is a potential diagnostic and prognostic biomarker for tumor initiation, metastasis and recurrence of cancers." (PMID 28969100, 2017). "Furthermore, the expression level of UCA1 was found to be associated with tumor clinicopathological features and patient prognosis." (PMID 27517147, 2016). "Overexpression of UCA1 has been reported to be associated with resistance to chemotherapeutic drugs, including 5-fluorouracil, cisplatin, gemcitabine, paclitaxel, docetaxel, gefitinib, cetuximab, doxorubicin, daunorubicin, tamoxifen, temozolomide, and trastuzumab, in many kinds of tumor cells 65-80." (PMID 36741256, 2023). "Using a xenograft animal model, we employed UCA1-depleted cells to evaluate UCA1’s role in tumor growth and metastasis." (PMID 41068676, 2025). "While the study did not define the independent role of miR-184, the findings suggest that the UCA1–miR-184 interaction contributes to tumour suppression during ART treatment." (PMID 41379397, 2025). "UCA1, a lncRNA significantly upregulated in chemotherapy-resistant tumor tissues and cell lines, inhibits miR-513a-5p, subsequently upregulating Stathmin 1 (STMN1) expression." (PMID 40191723, 2025). "UCA1 promotes tumor energy metabolism by increasing TGFβ1 expression, which enhances glucose uptake, lactate production, and ATP generation, supporting tumor cell survival and growth." (PMID 41437175, 2025). "Downregulation of miR-184 by UCA1 increased proliferation, cisplatin resistance, and reduced apoptosis, indicating that miR-184 normally functions as a tumour suppressor in this context." (PMID 41379397, 2025). "Significant relationships were also discovered between tumor severity and the lncRNAs UCA1 and MKLN1-AS level." (PMID 40703556, 2025). "On the contrary, overexpression of UCA1 in sensitive cell lines inhibited cisplatin-induced apoptosis and increased tumor growth." (PMID 39925739, 2025). "UCA1 acts as a sponge for miR-1-3p, an miRNA with a tumor suppressor function that significantly inhibits VM growth and formation." (PMID 40277941, 2025). "Several studies reported that the role of UCA1 in other malignant tumors and specifically its function in neoplasm, apoptosis, anti‐cancer drug resistance, metabolism, and crosstalk with miRNAs." (PMID 40231344, 2025). "UCA1 primarily promotes carcinogenesis by binding to potential tumour‐suppressive miRNAs, activating critical signalling pathways, and modifying transcriptional and epigenetic regulation." (PMID 38506091, 2024). "UCA1 was identified as one of the significantly differentially expressed lncRNAs between the five paired tumor and normal tissues." (PMID 38534790, 2024).
tumor (continued). "UCA1 assumes a multifaceted role in glycolysis, potentially steering the expression or functionality of critical enzymes, thereby directly influencing tumor cell glycolysis." (PMID 39286016, 2024). "By dictating the metabolic reprogramming of tumor cells and reshaping cellular metabolic pathways, UCA1 underpins tumor growth and sustenance." (PMID 39286016, 2024). "The MDA-MB-468 and HCC1937 cells also displayed decreased UCA1 levels, after their exposure to another tumor suppressor, ARID1A." (PMID 38534790, 2024). "The in vivo experiment showed that UCA1 increased the tumor volume and induced PTX resistance via the miR-613/CDK12 axis." (PMID 38534790, 2024). "Exosomes isolated from cetuximab‐resistant CRC cells have been found to modify the expression of UCA1, a prominent member among anti‐tumour lncRNAs." (PMID 38506091, 2024). "The reduction in tumor growth and size attributed to UCA1 knockdown was also observed in mice injected with primary endometrioid EC cells transfected with the UCA1 vector, thereby corroborating the in vitro findings." (PMID 38534790, 2024). "This metabolic versatility permits tumor cells to withstand metabolic stress, with UCA1 playing a pivotal role." (PMID 39286016, 2024). "Two of the referenced studies additionally conducted in vivo experiments, both demonstrating that UCA1 silencing suppressed tumor development and enhanced apoptosis in mice." (PMID 38534790, 2024). "The in vivo experiment revealed that UCA1 silencing suppressed cancer development, while UCA1 was overexpressed in the endometrioid EC tissues and closely correlated with tumor growth, metastasis, and poor overall survival." (PMID 38534790, 2024). "Both findings suggest the amplified capability of UCA1 to induce migration, invasion, and tumor development in BC." (PMID 38534790, 2024). "In the in vivo experiment, UCA1 enhanced cancer proliferation, while the tissue specimens analysis showed that UCA1 promotes tumor growth by suppressing p27." (PMID 38534790, 2024). "NSCLC tissues have high levels of LncRNA-UCA1, and tumor cell proliferation is inhibited by UCA1 silencing." (PMID 38850527, 2024). "This evidence suggests that UCA1 downregulation suppresses tumor growth by inducing cell cycle arrest in MCF7 cells." (PMID 38534790, 2024). "UCA1 overexpression abolished the tumor-suppressing effects of ARID1A in vivo, confirming the in vitro results." (PMID 38534790, 2024). "UCA1 overexpression mainly accounts for enhanced tumor proliferation and increased drug resistance, while also being associated with some clinicopathological features, such as a high histological grade or poor prognosis." (PMID 38534790, 2024). "Further analysis revealed that UCA1 knockdown significantly inhibited the invasive and migratory abilities of tumor cell lines." (PMID 38725621, 2024). "The overexpression of UCA1 promotes tumor cisplatin resistance in some cancers, similar to the other lncRNAs discussed in this section." (PMID 38256203, 2024). "UCA1 was once again shown accountable for driving aggressive tumor growth, through its interactions with proteins such as KIF20A, and by sponging different miRNAs, such as miR-299-3p, miR-145, and miR-155." (PMID 38534790, 2024). "Ultimately, by catalyzing glycolysis, UCA1 supplies the requisite energy and biosynthetic precursors for tumor cells, bolstering their invasive and metastatic prowess." (PMID 39286016, 2024). "LncRNAs, such as HOTAIR, PCGEM1, H19, and UCA1, are dysregulated in many types of tumor tissues and can function either as oncogenes or tumor suppressors through regulating cancer cell growth, apoptosis, and invasion." (PMID 38195623, 2024). "At present, multiple studies on UCA1 in various tumor types have proved the possibility of UCA1 as a target for cancer treatment." (PMID 36741256, 2023). "When 5637 cells knocked down UCA1 were injected into nude mice for culture, the growth rate of the transplanted tumor slowed down, and the weight decreased." (PMID 37215997, 2023).
tumor (continued). "Recent studies have verified the overexpression and oncogene functions of UCA1 in different tumours." (PMID 36831352, 2023). "Specifically, UCA1 can serve as a sponge of miRNAs to regulate tumour growth, metastasis, drug resistance and mitochondrial functions." (PMID 36831352, 2023). "Functionally, UCA1 carried out an oncogenic role by regulating the miR-582-5p/BRCC3 signal to promote tumor progression." (PMID 37564930, 2023). "The lncRNA urothelial carcinoma associated 1 (UCA1) is one of the best studied purely retroviral HERV gene products with major effects on cancer progression, tumor growth, apoptosis, invasion, radioresistance, chemoresistance, and metabolism." (PMID 36979914, 2023). "Panc-1 cells with UCA1 downregulation or control cells were transplanted into mice, and tumor growth was monitored." (PMID 37564930, 2023). "The tumor growth, size and weight were significantly decreased in the mice with downregulation of UCA1 than that in control group." (PMID 37564930, 2023). "Tumor regression can be induced by knocking down UCA1, which leads to the downregulation of slug, a molecular effector protein." (PMID 37245177, 2023). "The knockdown of UCA1 inhibited reversing this polarization trend and impaired the tumor growth and invasion." (PMID 37637063, 2023). "Our study reported a novel signaling pathway that UCA1 promoted tumor progression by regulating miR-582-5p/BRCC3." (PMID 37564930, 2023). "On the other hand, tumor growth promoters like prostate cancer-associated transcript 1 (PCAT1), PVT1, and urothelial cancer associated 1 (UCA1) act as transcriptional repressors, a mir-145-5P sponge, and a P13K/AKT pathway activator." (PMID 37021836, 2023). "We also found that elevated expression of TM4SF1-AS1, CASC8, UCA1, and LINC00941 was associated with C1, C2, and C6, suggesting a tumor-promoting effect and poor prognosis." (PMID 36871072, 2023). "Tumor proliferation is usually promoted by HypoExo cargoes, such as exosomal lncRNA UCA1 from hypoxic bladder cancer cells and exosomal miR-410-3p from hypoxic CRC cells, and apoptosis of tumor cells is usually inhibited by exosomes under hypoxia." (PMID 35039054, 2022). "UCA1 can interact with various miRNAs, which then change gene expression profiles and control tumor progression." (PMID 36232884, 2022). "Tumor volume and tumor weight were significantly smaller in the Si-UCA1 group while were dramatically increased in the over-METTL14 group compared with the control group." (PMID 35178087, 2022). "Exosomal transfer of lncRNA UCA1 promoted cell migration and tube formation of human umbilical vein endothelial cells (HUVECs), contributing to angiogenesis and tumor growth." (PMID 35444652, 2022). "After oe-UCA1 treatment, the tumor volume and tumor weight in mice had clearly increased, but this effect was abrogated by sh-LAMC2." (PMID 36483681, 2022). "In effect, hypoxic exosomal expressed UCA1 promotes angiogenesis and tumor growth via the miR-96-5p/AMOTL2/ERK1/2 axis." (PMID 36233088, 2022). "Urothelial cancer associated 1 (UCA1) was also upregulated in CRC and promoted tumor cell proliferation." (PMID 36139062, 2022). "UCA1 primarily promotes tumorigenesis by binding to probable tumour-suppressive miRNAs, activating several key signalling pathways and altering transcriptional and epigenetic regulation." (PMID 34976187, 2022). "To examine the correlation between TWIST1 and UCA1, the lncRNA that had been expressed in all three cell lines, we performed real-time PCR for UCA1 in twenty tumor and tumor-adjacent normal tissue samples with confirmed overexpression of TWIST1 (logFC > 2)." (PMID 35949302, 2022). "For instance, hypoxic cells remodel the tumor microenvironment to facilitate tumor growth and development by secreting oncogenic lncRNA UCA1 enriched exosomes." (PMID 34869309, 2021). "Next, we further determined the expression of UCA1 in 46 pairs of CRC tumor tissues collected from our hospital by qRT-PCR." (PMID 34809621, 2021).
tumor (continued). "Our data also show high expression levels of UCA1 in tumor tissues compared to matched normal tissues." (PMID 34054950, 2021). "Tumorigenic assays in nude mice showed that UCA1 knockdown significantly inhibited tumor growth and reduced cisplatin resistance." (PMID 34544452, 2021). "It revealed that the expression level of UCA1 in the tumor tissues from the shUCA1 group was significantly lower than that in the shNC group." (PMID 34238213, 2021). "Despite several studies have reported a positive correlation between overexpressed lncRNA UCA1 and tumor progression; however, contradictory findings were reported." (PMID 33936199, 2021). "Invasion and metastasis: UCA1 overexpression increased invasion and migration, while its silencing inhibited tumor progression via several mechanisms." (PMID 34322395, 2021). "We also analyzed their expression in four GEO datasets, which confirmed the elevated expression of UCA1 in CRC tumor and the decreased expression of PGM5-AS1 in GSE102340, GSE126092, GSE109454, and GSE115856 datasets." (PMID 34212174, 2021). "Through the ceRNA network, UCA1 can regulate the expression of miR-203-targeted transcript ZEB2 that is a transcription factor related to tumor metastasis." (PMID 34464437, 2021). "Previous studies have suggested that overexpression of UCA1 in CRC indicates a large tumor, advanced TNM stage, deeply infiltrated lymph node, positive lymph node metastasis and poor OS." (PMID 33777227, 2021). "UCA1 is highly expressed in tumor tissues, regulating the metastasis, invasion, proliferation, and apoptosis of tumor cells." (PMID 33743811, 2021). "Tumor xenograft models were employed to further evaluate the effect of UCA1 on tumor growth and cisplatin resistance in vivo." (PMID 34544452, 2021). "LncRNA UCA1 was first discovered in bladder cancer and can promote tumor cell proliferation and metastasis." (PMID 33879677, 2021). "The tumor volume and weight were reduced in the Exo + UCA1-siRNA group and the Exo + miR-122-5p mimic group relative to that in the Exo + siRNA-NC group and the Exo + mimic-NC group (all P < 0.05)." (PMID 34053467, 2021). "By analyzing the TCGA-COAD datasets, UCA1 was found to be highly expressed in samples with tumor burden compared to that in the normal group." (PMID 34733326, 2021). "UCA1 acted as an endogenous sponge for several tumor suppressor miRNAs, such as miR-122, miR-204-5p, and miR-135a." (PMID 34322395, 2021). "The tumor volumes were significantly less and the tumor weight also much lower in UCA1 KD group than that in vector control group." (PMID 34809621, 2021). "For example, tumor cells can produce lncRNA UCA1-rich exosomes, which are transported to normoxic cells to promote tumor cell malignant phenotypes under hypoxia." (PMID 34868904, 2021). "The existing research results showed that UCA1 participated in cell proliferation, migration, and invasion to regulate tumor progression." (PMID 34544452, 2021). "The overexpressed lncRNA UCA1 regulated tumor progression through the recruitment of EZH2 to the promoter of both tumor suppressor p21 and E-cadherin that resulted in their suppressed expression." (PMID 33936199, 2021). "The tumor growth was most significantly inhibited in mice following UCA1 knockdown compared with that in the NC groups, indicating that UCA1 played an important role in regulating the growth of LUAD cells in vivo." (PMID 34544452, 2021). "First, HNRNPA2B1 has been reported to synergize with a long noncoding RNA urothelial cancer associated 1 (UCA1) to enhance KRAS expression and activity, ultimately facilitating CSCs properties and tumor growth in PC." (PMID 34586737, 2021). "As reported in previous literature works, lncRNA UCA1 and lncRNA RP11-361F15.2 were associated with the tumor-promoting function of TAMs on OS progression." (PMID 34686652, 2021).
tumor (continued). "The results of in vivo experiments further showed that treatment with Gem reduced the tumor volume and weight of mice with lncRNA UCA1 knockdown as well as decreasing the positive expression rate of Ki67 in the tumor tissues." (PMID 34868904, 2021). "As an example, expression analysis of UCA1 lncRNA in colorectal cancer (CRC) patients showed upregulation in tumor biopsies and downregulation in serum exosomes when compared to their normal counterparts." (PMID 32932969, 2020). "In sum, our findings suggest that the UCA1/miR-203/HK2 axis contributes to EC development by reprogramming tumor glucose metabolism, providing new insight into the management of EC patients." (PMID 33204264, 2020). "Firstly, we found that upregulated UCA1 expression enhances the malignant phenotypes of EC, including poor outcome, larger tumor size, positive lymphatic invasion, and advanced pathological stages." (PMID 33204264, 2020). "In vivo studies demonstrated that UCA1 knockdown induced the smallest tumor volume and weight and so on in nude mice." (PMID 31996265, 2020). "In the tumor tissues of SC groups, MALAT1 and AFAP1-AS1 showed a significant reduction after being treated with high-dose Vc, while the expression of UCA1, which showed a reduction trend in vitro, was increased in SC tumor tissue after high-dose Vc." (PMID 33293956, 2020). "In order to explore the effect of UCA1 knockout in the regulation of tumor growth in vivo, we further examined the function of UCA1 using AGS cell subcutaneous xenograft mouse model." (PMID 31272462, 2019). "Knockdown of UCA1 inhibits Akt phosphorylation and diminishes invasiveness of tumor cells induced by macrophage." (PMID 31480503, 2019). "It was proven that UCA1 acted as a ceRNA of the tumor suppressor miR-28-5p via 3′UTR binding and thereby impeded the repression of HOXB3, which promoted cancer cell proliferation and invasion." (PMID 31744051, 2019). "UCA1 levels were significantly higher in tumor tissues compared with adjacent healthy tissues in the majority of patients with LSCC." (PMID 31336999, 2019). "In consideration of the tumor-promoting effects of UCA1, more studies with a large sample size need to be conducted to verify the conclusion." (PMID 31297033, 2019). "In conclusion, we present here that UCA1 functions as an onco-lncRNA promotes GC cells proliferation, migration and inhibits GC cells apoptosis by repressing anti-tumor miRNAs as miR-26a and miR-26a." (PMID 31272462, 2019). "For example, Hsa-miR-1 suppresses expression of the UCA1 via an Ago2-slicer-dependent signaling and structure recognition 3-untranslated regions (3-UTRs) of UCA1 to play tumor suppressive roles." (PMID 31133028, 2019). "Clinicopathological evidence obtained from CRC patients highlighted that the expression of UCA1 was correlated with lymph node metastasis, tumor stage, and poor prognosis." (PMID 31744051, 2019). "In metastatic BC patients, UCA1 is upregulated in tumor tissues, and the level of UCA1 is negatively correlated with prognosis." (PMID 31480503, 2019). "In vivo studies showed that overexpression of UCA1 promoted the in vivo tumor growth of U87 cells in the nude mice." (PMID 31596734, 2019). "Meanwhile, the level of anti-tumor miRNAs (miR-26a, miR-26b, miR-193a and miR-214) that directly interact with UCA1, was increased in the UCA1-KO tumors." (PMID 31272462, 2019). "High expression levels of lncRNA HEGBC, PAGBC, PVT1 and UCA1 predicted high tumor node metastasis (TNM) stages, while lncRNA LET, GCASPC and MEG3 indicated low TNM stages." (PMID 31297033, 2019). "The tumor size growth curve over 6 weeks clearly demonstrated that the tumors from nude mice injected with UCA1 grew much faster than the other groups, and the difference is significant (p < 0.01)." (PMID 31695578, 2019). "We found that expression of Ki-67, a cell proliferation marker, and MMP-9, a cell metastatic marker in xenograft tumor tissue samples were inhibited in LV-sh-UCA1, in contrast with LV-sh-con." (PMID 31798345, 2019).